AKT1 (AKT serine/threonine kinase 1)
Diseases named in the same sentence as AKT1 in open-access papers (continued):
Sharing a sentence is not in itself a finding about the gene and the disease.
psychosis (continued). "In the case-sibling design, patients with the AKT1 rs2494732 CC genotype displayed approximately twofold higher odds of being diagnosed with psychotic disorder when having used cannabis in comparison with TT homozygotes." (PMID 28822116, 2018). "Among daily cannabis users, individuals with the AKT1 rs2494732 CC genotype demonstrated a sevenfold increase in the odds of developing psychosis compared to the AKT1 rs2494732 TT homozygotes." (PMID 28822116, 2018). "The analysis showed an increasing probability of suffering from a psychotic disorder in cannabis users depending on DRD2/AKT1 (N=450, likelihood ratio test=7.66; P=0.022)." (PMID 27336035, 2015). "A multivariable logistic regression adjusting for the modeled potential confounders showed a significant interaction between DRD2 rs1076560/AKT1 rs2494732 genotypes and lifetime cannabis use on probability of suffering from a psychotic disorder." (PMID 27336035, 2015). "Indeed, Decoster and colleagues recently reported that a genetic variation in the AKT1 gene may mediate cannabis-associated effects on the expression of psychosis via a cannabinoid-regulated AKT1/GSK-3 signaling mechanism that lies downstream of the dopamine D2 receptor." (PMID 25426017, 2014). "Studies published in Translational Psychiatry and Biological Psychiatry provide data suggesting that the AKT1 variant rs2494732 (particularly the C/C genotype) increases sensitivity to the acute psychotic effects of THC and modifies the risk of psychosis with frequent use." (PMID 41465160, 2025). "COMT and AKT1 serve as nonspecific risk markers but as genetic modifiers and predictor genes, respectively, in a more complex gene-environment model of psychosis risk." (PMID 41127784, 2025). "No differential methylation of AKT1 relevant to psychosis risk has been identified in other studies reported on MethBank." (PMID 35327363, 2022). "However, the fact that AKT1 is relevant to the biology of psychotic symptoms suggests that this might be a promising direction for novel therapeutics for cannabis-induced psychosis." (PMID 26882038, 2016). "Another research found that polymorphism of AKT1 gene may be related to the use of cannabis and to the developing of psychosis, but not specifically for bipolar patients." (PMID 26097750, 2015). "If so, then the effect of smoking to decrease overall AKT1 methylation but to increase relevant TDO2 and MCHR1 methylation may indeed have functional relevance to psychosis." (PMID 35327363, 2022). "Whereas MCHR1 has repeatedly shown significant genetic linkage to psychotic disorders as a single gene, AKT1 and TDO2 have not in a reproducible manner, yet, that does not preclude these loci from exerting relevant effects as a result of environmentally-induced epigenetic changes." (PMID 35327363, 2022). "Single-nucleotide polymorphisms in the AKT1 and catechol-O-methyltransferase (COMT) genes have been implicated in the interaction between cannabis, psychosis and cognition, but no studies have examined their impact on an individual's acute response to smoked cannabis." (PMID 26882038, 2016).
Myocardial fibrosis (25 papers, 2018 to 2026). "Research indicates that in the early stages of myocardial fibrosis, AKT1 activity significantly increases and plays a critical role in regulating cardiomyocyte apoptosis and metabolism." (PMID 40552149, 2025). "Subsequent studies confirmed the protective effect of H2S against diabetes-induced myocardial fibrosis and demonstrated that it was also associated with the attenuation of autophagy through upregulation of the PI3K/Akt1 signaling pathway." (PMID 34205197, 2021). "Research has shown that the expression and activation of Akt1 are involved in the progression of myocardial fibrosis; Jun can serve as an important transcription factor in the cell and widely involves in tumor regulation, smooth muscle proliferation, and apoptosis." (PMID 35722148, 2022). "The immunoproteasome subunit PSMB10 alleviates myocardial fibrosis by reducing PTEN degradation and suppressing AKT1 activation." (PMID 40098617, 2025). "H2S has been identified as a potential therapeutic agent for myocardial fibrosis, exerting its effects through the attenuation of myocardial autophagy and the activation of the PI3K/AKT1 signaling pathway." (PMID 38790620, 2024).
myocardial ischemia (25 papers, 2013 to 2025). A disorder of cardiac function caused by insufficient blood flow to the muscle tissue of the heart. "Our results are in accordance with other reports that crocin activated Akt1 in microglial cells of diabetic retinopathy and myocardial ischemia/reperfusion injury." (PMID 35655597, 2022). "However, it remains unknown whether MKK3 and Akt-1 are involved in HDAC inhibition-induced myocardial protection in acute myocardial ischemia and reperfusion injury." (PMID 23762381, 2013). "Consistent with findings in infarcted myocardium, in acute myocardial ischemia and reperfusion model, our observation also showed the HDAC inhibition-induced cardiac protection was lost in Akt-1−/− mice." (PMID 23762381, 2013). "However, it remains unknown whether HDAC inhibition modulates myocardial ischemia and reperfusion injury through MKK3 and/or Akt-1." (PMID 23762381, 2013).
sarcoma (25 papers, 2011 to 2025). A usually aggressive malignant neoplasm of the soft tissue or bone. "Similarly, areca nuts may also activate other pathways through AKT1, including the rat sarcoma (Ras) and repressor/activator protein 1 (RAP1) signaling pathways, as determined via KEGG analysis." (PMID 39027148, 2024). "In addition, it is reported that inhibiting AKT1/2 reduces NANOG expression in sarcoma CSC to reverse chemotherapy resistance, NANOG mediates the radio-resistance of tumor cells through AKT and Notch pathways partially." (PMID 38561775, 2024).
fibrosarcoma (24 papers, 2014 to 2026). A malignant mesenchymal fibroblastic neoplasm affecting the soft tissue and bone. "Additionally, AKT1 has been shown to promote migration of fibrosarcoma cells through NF-κB." (PMID 35741006, 2022). "Rhabdomyosarcomagenesis involves, in part, the prolonged activation of serine/threonine kinases such as AKT, and we have previously shown that AKT1 and AKT3 phosphorylation stabilizes the TBX3 protein in chondrosarcoma/fibrosarcoma and melanoma, respectively." (PMID 32098189, 2020). "Indeed, in melanoma, AKT3 is the most abundant isoform and AKT phosphorylation of TBX3 enhances protein stability, nuclear localisation and transcriptional activity; in fibrosarcoma and chondrosarcoma, AKT1 is the predominant isoform and it maintains high levels of TBX3." (PMID 32098189, 2020).
hepatitis B (23 papers, 2020 to 2026). "Most targets were associated with cancer, the PI3K-AKT signaling pathway and hepatitis B. The targets with the largest number of participating pathways were AKT1, RELA, and MAPK1, which participate in 21, 19, and 19 pathways, respectively." (PMID 36591458, 2022). "The 2 components of Radix Paeoniae Alba play an auxiliary role in treating hepatitis by binding targets AKT1 and JUN and activating Hepatitis B, Hepatitis C, and other pathways." (PMID 38050220, 2023). "Topological analysis indicated that AKT1, FOS, CCL2, CXCL8, and CXCL10 are hub genes; TLR signaling pathway, cellular senescence, hepatitis B, and chemokine signaling pathway are key pathways in the IGP network." (PMID 33623529, 2021). "We identified quercetin acted on the targets (AKT1, FOS, CCL2, and CXCL8) through key signal pathways (toll-like receptor signal pathway, hepatitis B, cell senescence, and chemokine signaling pathway) to exert treatment effects on CHB by use of a network pharmacological method." (PMID 33623529, 2021). "In this study, AKT1 and CXCL8 are enriched in hepatitis B (hsa05161), which may be involved in the regulation of HBV replication." (PMID 33623529, 2021).
papillary thyroid carcinoma (23 papers, 2015 to 2026). "APOE suppresses ferroptosis in papillary thyroid carcinoma (PTC) via the PI3K/AKT1 pathway, elevating GPX4/FTH1 expression while reducing Fe2+ accumulation." (PMID 41390817, 2025). "In thyroid papillary carcinoma, somatic mutations in PIK3CA and AKT1 are found in limited cases." (PMID 38501028, 2024).
epilepsy (22 papers, 2016 to 2026). A brain disorder characterized by episodes of abnormally increased neuronal discharge resulting in transient episodes of sensory or motor neurological dysfunction, or psychic dysfunction. "Our results proved that XYC exerted favorable effect on epilepsy by modulating the gut microbiota and serum lipid metabolic, especially neuroinflammation and glycerophospholipid metabolism by regulating the AKT1, INS and IL-6 expression levels." (PMID 40880740, 2025). "From the evidence chains we see that Ibudilast, through its association with modulating both the cAMP and cGMP pathways, is linked to FXS through the proteins AKT1 and MEF2C, and their association with epilepsy." (PMID 38977662, 2024). "The PI3K/AKT1 signaling pathway is activated in epilepsy animal models and in patients who have temporal lobe epilepsy (TLE) with hippocampal sclerosis." (PMID 32781725, 2020). "Notably, AKT1, INS, and IL-6 emerged as central nodes, which were functionally associated with lipid metabolic and inflammation processes, particularly glycerophospholipid metabolism, suggesting their potential as key therapeutic targets of XYC for epilepsy treatment." (PMID 40880740, 2025).
ovarian tumors (22 papers, 2008 to 2024). "AKT1, a serine/threonine kinase, is an integral part of the PI3K/AKT signaling pathway, often found dysregulated in ovarian tumors." (PMID 37964873, 2023). "Ovarian tumor cells with an AKT1 knockdown show impaired tumor progression and metastasis, whereas an AKT2 knockdown leads to increased tumor progression and metastases formation." (PMID 31752925, 2019). "Inhibition of Akt1, both in the tumor cells and in our mice model, potently decreased ovarian tumor growth and decreased tumor proliferation, angiogenesis, and metastasis." (PMID 27533079, 2016). "In the present study, we indicated that FHL2 is a key regulator of AKT1 gene expression, at least in the ovarian tumor cell lines." (PMID 27415427, 2016). "Interestingly, the Akt1 inhibitor A-674563 has also been shown to reduce survival of endothelial colony forming cells and inhibit vasculogenesis in vitro, which corresponds to the reduced microvessel density that we saw in ovarian tumors induced with Akt1 KD cells." (PMID 27533079, 2016). "Rictor was associated more with AKT1 rather than AKT2, and overexpression of Rictor facilitated IGF-1-induced AKT1 activation, whereas silencing of AKT1 but not AKT2 inhibited IGF-1- induced ovarian tumor cell migration." (PMID 22680924, 2012).
brain tumor (21 papers, 2011 to 2024). "AKT1 overexpression also enhances physical interaction of microglia with AKT1+-tumor cells in a zebrafish model of brain tumors." (PMID 34690699, 2021). "To address these questions, we made use of our recently published zebrafish brain tumour model to analyze interactions between microglia and neoplastic AKT1 overexpressing cells." (PMID 31313988, 2019). "Previously we described direct cellular interactions between microglia and AKT1+ brain tumour cells in zebrafish." (PMID 31313988, 2019). "In summary, these experiments show that macrophages and microglia promote proliferation of AKT1-positive cells from the earliest stages of brain tumor growth." (PMID 29465400, 2018). "By overexpression of human dominant active AKT1 in neural cells, we induced abnormal cellular growth and morphology, increased proliferation and early differentiation, mimicking the earliest stages of brain tumor growth." (PMID 29465400, 2018). "In contrast to AKT1, STAT3 phosphorylation was not significantly changed after stimulation of LN18 cells with S1P despite a previously reported down-regulation of phosphorylated STAT3 in brain tumor stem cells after stimulation with the S1P analogue fingolimod." (PMID 26887055, 2016).
steatosis (21 papers, 2013 to 2025). Increased lipid within the cytoplasm of cells. "Additionally, oenocyte-specific loss of akt1 also led to steatosis phenotypes indicating that the Pi3K-Akt1 pathway in the oenocytes regulates lipid homeostasis." (PMID 33107824, 2020). "Berberine reduced steatosis in MIHA and HepG2 cells by mechanism associating with up-regulation of miR-373, which decreased its mRNA level target gene AKT serine/threonine kinase 1 (AKT1), resulting in the suppression of AKT-mTOR-S6K signaling pathway in hepatocytes." (PMID 32265720, 2020). "Moreover, after the treatment with the association, the increment in the expression of the genes related to cell survival, AKT1, MAPK8, PIK3CA (four times), and FAS (eight times), and to anti-inflammatory signaling, IL10 (four times), was observed in respect to the steatosis control." (PMID 36770927, 2023).
bipolar disorder (20 papers, 2008 to 2025). A disorder of the brain that causes unusual shifts in mood, energy, activity levels and the ability to carry out day-to-day tasks. "Data on the relationship between AKT1 and bipolar disorder is scarce however." (PMID 22393424, 2012). "mRNA expression of AKT1 and mTOR are downregulated in bipolar depression, and may induce autophagy." (PMID 34122166, 2021). "For example, decreased AKT1 and mTOR mRNA expression was observed in bipolar disorder patients without medications compared with healthy controls." (PMID 35111368, 2022).
hyperlipidemia (20 papers, 2018 to 2025). "After exploring the PPI network of DO for hyperlipidemia, the key targets of DO for hyperlipidemia included AKT1, TNF, PPARG, ADIPOQ, and APOB." (PMID 35502176, 2022). "The results from the PPI analysis showed that the targets for YCWL relating to the treatment of hyperlipidemia mainly involved AKT1, IL6, VEGFA, and PTGS2." (PMID 34746316, 2021). "Overall, AM alleviated acquired hyperlipidemia through regulating lipid metabolism, and AKT1, VEGFA, CCND1 and ESR1 might be the key targets." (PMID 35267929, 2022). "Additionally, AKT1 inhibition ameliorates hyperlipidemia, a common metabolic complication in NASH patients." (PMID 36559697, 2022). "So far, we believe that AM may alleviate hyperlipidemia induced by HFD by downregulating the AKT1 and CCND1 protein levels and upregulating the levels of VEGFA and ESR1 protein." (PMID 35267929, 2022). "The previous bioinformatics analysis results showed that AM might alleviate hyperlipidemia by HFD through regulating the expression of four key targets (AKT1, VEGFA, CCND1 and ESR1)." (PMID 35267929, 2022). "The results of network pharmacology and bioinformatics analysis in the current study showed that AM might alleviate acquired hyperlipidemia by downregulating the expression of AKT1 and CCND1 and upregulating the expression of VEGFA and ESR1." (PMID 35267929, 2022). "More importantly, AKT1, VEGFA, CCND1, ESR1 are the key targets of AM to alleviate hyperlipidemia induced by HFD." (PMID 35267929, 2022). "In summary, AKT1, TNF, PPARG, ADIPOQ, and APOB may be targets for the action of DO in the treatment of hyperlipidemia." (PMID 35502176, 2022). "Supportably, it could be seen that AKT1 and CCND1, VEGFA and ESR1 were involved in hyperlipidemia-related diseases and several studies had uncovered the regulation of AM on these genes in different diseases." (PMID 35267929, 2022). "The network analysis uncovered that naringenin, isorhamnetin, and taxifolin might be the compounds in DO that are mainly in charge of its roles in hyperlipidemia and might play a role by modulating the targets (including PPARG, ADIPOQ, AKT1, TNF, and APOB)." (PMID 35502176, 2022). "In conclusion, AM alleviated acquired hyperlipidemia in mice fed with HFD through regulating lipid metabolism, and AKT1, VEGFA, CCND1 and ESR1 may be the key targets." (PMID 35267929, 2022). "So far, we believe that AM may reduce the expression of AKT1 and CCND1 and increase the expression of VEGFA and ESR1 to alleviate hyperlipidemia induced by HFD." (PMID 35267929, 2022).
astrocytoma (19 papers, 2009 to 2025). "We performed a systematic mutational analysis of the complete coding sequence of the AKT1 gene in a panel of 109 tumor GBM samples and nine high grade astrocytoma cell lines." (PMID 19461960, 2009). "To definitively assess this hypothesis, we successfully sequenced the complete coding sequence of AKT1 in 109 GBM tumor samples and nine high grade astrocytoma cell lines." (PMID 19461960, 2009).
polycystic ovary syndrome (19 papers, 2020 to 2026). A disorder that manifests as multiple cysts on the ovaries. "Moreover, gene polymorphisms in AKT1 and AKT2 were associated with T2D, polycystic ovarian syndrome (PCOS) and cancer in the Chinese population." (PMID 37754255, 2023).
acute kidney injury (18 papers, 2019 to 2026). Sudden and sustained deterioration of the kidney function characterized by decreased glomerular filtration rate, increased serum creatinine or oliguria. "So, inhibition of the AKT1 gene could prove beneficial in mitigating kidney damage.AKT1-mediated mitochondrial dysfunction may play an important role in nephropathy and consequent renal failure." (PMID 40435181, 2025). "In instances of insufficient or absent AKT1 expression, the expansion of RIF and dedifferentiation of renal tubular cells during the transition from acute kidney injury to CKD were significantly slowed." (PMID 41142245, 2025).
autoimmune disease (18 papers, 2017 to 2024). A disorder resulting from loss of function or tissue destruction of an organ or multiple organs, arising from humoral or cellular immune responses of the individual to their own tissue constituents. "AKT1 is an essential regulator in AKT1/mTOR signaling pathways, and this pathway in autoimmune diseases such as SS can regulate the IL-17 effect." (PMID 36248435, 2022). "As an isoform, Akt1 has been proved to correlate with autoimmune diseases such as SLE and multiple sclerosis." (PMID 35990826, 2022). "miR-374b was previously found to inhibit cell growth and promote apoptosis in T cell lymphoblastic lymphoma via suppression of AKT1 and Wnt-16, which were correlated with immune activities in autoimmune diseases." (PMID 34036107, 2021). "Furthermore, consistent with the AKT1/mTOR pathway regulating IL-17 in various autoimmune diseases, the miR-let-7d-3p knockout increased IL-17 levels via the AKT1/mTOR pathway, and co-overexpressing AKT1 with miR-let-7d-3p recovered IL-17 expression." (PMID 39062113, 2024). "AKT1 can influence platelet activation, while TNF is involved in the regulation of a wide spectrum of biological processes including cell proliferation, differentiation, apoptosis, lipid metabolism and coagulation, and it has been implicated in autoimmune diseases." (PMID 35911404, 2022).
pancreatic ductal adenocarcinoma (18 papers, 2012 to 2026). An infiltrating adenocarcinoma that arises from the epithelial cells of the pancreas. "For example, in pancreatic ductal adenocarcinoma, miR-637 over-expression significantly suppressed cell proliferation and induced apoptosis through inhibiting expression of Akt1." (PMID 33209200, 2020). "Akt1 activity in combination with KRAS oncogenic mutant could accelerate pancreatic progression toward invasive pancreatic ductal adenocarcinoma." (PMID 35154607, 2021).